APOE (apolipoprotein E)
Diseases named in the same sentence as APOE in open-access papers (continued):
Sharing a sentence is not in itself a finding about the gene and the disease.
kidney disease (46 papers, 2005 to 2025). "HN has also been shown to reduce inflammation, apoptosis, and macrophage infiltration in apolipoprotein E (ApoE)-deficient mice during early stages of kidney disease." (PMID 37538245, 2023). "Immunohistological analyses of apoB/apoE amount in the glomeruli in renal disease found its association with accelerated progression of the renal disease itself." (PMID 31752189, 2019). "A prospective study from the atherosclerosis in risk in communities study of middle aged adults demonstrated that the APOE ε4 allele was associated with lower risk of kidney disease progression." (PMID 22874105, 2012). "The interconnection between HDL and renal function is confirmed by the fact that genetic HDL defects can lead to kidney disease; in fact, mutations in apoA-I, apoE, apoL, and lecithin–cholesterol acyltransferase (LCAT) are associated with the development of renal damage." (PMID 33807271, 2021). "Therefore, we utilized the apoE KO mouse model to investigate the potential for a direct causal role of lipids on the progression of kidney disease." (PMID 32581831, 2020). "The inverse association between the e4 allele and prevalence of low-GFR cases (GFR<75 ml/min/1.73 m2) is an important finding in determining whether APOE variation is a risk factor for kidney disease." (PMID 19852818, 2009). "Model 7 showed significantly lower average values in men, faster average decrease in higher APOE‐npscore, lower average values in those with higher APOE‐npscore, faster average decrease in those with Stage 3 kidney disease, and lower average values in A+." (PMID 38970274, 2024). "Our major ideas–including the analogy of HAE to C1-INH insufficiency in the CNS, CR1 and apoE as factors in AD, plus Factor H in ocular and renal disease – are grounded in human studies." (PMID 33746710, 2021). "We evaluated the association of apolipoprotein E allelic frequency with prevalent CKD and rate of progression of kidney disease in older adults in the Cardiovascular Health Study." (PMID 22874105, 2012). "Observational epidemiology studies have supplied population-based evidence of the effect of APOE variations on prevalence and progression of kidney disease." (PMID 19852818, 2009). "Several studies have produced null results from investigations of ApoE and renal disease, but were generally underpowered." (PMID 19852818, 2009). "Variants in NOS3 and APOE, and the DMR on chromosome 14, appear to be associated with established kidney disease and may play a central role in the accelerated decline of kidney function in MeN." (PMID 40429630, 2025). "However, the effectiveness of using apoE−/− mice to study renal disease is blunted by the fact that feeding these mice standard chow results in aortal and renal pathological features only late in life, at 24 and 36 weeks of life, respectively." (PMID 24972137, 2014). "While it is known that B6 mice deficient in Fas (lpr) or FasL (gld) display mild or no kidney disease, the gld.apoE−/− model develops glomerular tuft enlargement and significant inflammatory cell infiltrate to the kidney." (PMID 23577189, 2013). "Although B6 mice deficient in Fas (lpr) or FasL (gld) display mild or no kidney disease, the lack of apoE associated with the gld mutation induces significant kidney disease." (PMID 23577189, 2013). "In an apolipoprotein E-deficient atherosclerotic mice model, not a kidney disease model, Ervinna et al41 demonstrated that anagliptin exerted an antiatherosclerotic effect through inhibition of the inflammatory reaction of monocytes and inhibition of smooth muscle cell proliferation." (PMID 28761658, 2017). "In addition, research of CKD and ApoE should be directed towards the elucidation of the molecular biology of kidney disease and mechanisms through which different forms of APOE may play a modulating role." (PMID 19852818, 2009).
kidney disease (continued). "Previous studies have demonstrated that apoE−/− mice fed a HFD develop aortal and renal diseases much more rapidly than if they were fed standard chow." (PMID 24972137, 2014). "Accordingly, the apoE−/− mice were fed a HFD and developed an earlier onset of renal disease in our study." (PMID 24972137, 2014). "Our findings suggest that vascular function of the thoracic aorta does not appear to be further impaired in apoE-/- mice 12-weeks following kidney disease when mice consume a standard chow diet." (PMID 25799529, 2015).
brain disorder (26 papers, 2013 to 2025). A disease affecting the brain or part of the brain. "Finally, emerging large human cross-correlated lipidomic to brain disease risk can provide personalized medicine based on APOE genotype and specific neuronal responses to lipid stress." (PMID 41278977, 2025). "Although mounting evidence points to the potentially complex interaction between these two brain disorders in which ApoE might play a role, the underlying mechanisms are largely unknown." (PMID 28934977, 2017). "Therefore, our results indicate that the APOE ε4 allele-associated alteration in global network topology tends toward increasing randomness, resulting in less efficient information flow in the brain, which is generally associated with brain disease." (PMID 24349461, 2013). "This idea was investigated in an ApoE knockout (ApoE-/-) rat model, since the ApoE gene is reported to be involved in the development of lipid and brain disorders." (PMID 36104381, 2022). "DAM represent a key microglial subpopulation present across several brain disorders and is dependent on triggering receptor expressed on myeloid cells 2-apolipoprotein E (TREM2-APOE) signaling." (PMID 34107254, 2021). "There are different investigations demonstrating that APOE genotype can influence the clinical phenotype of brain diseases during adulthood." (PMID 30677746, 2019). "The SNPs in APOE have also been related to neuroimaging measures in brain disorders such as MCI and AD44." (PMID 28358032, 2017). "The APOE protein participates in several brain disorders, including AD, MS, traumatic brain lesion and Creutzfeldt–Jakob disease, raising the possibility that ApoE may also play a significant role in the development of PD." (PMID 35076620, 2022). "Apolipoprotein E (ApoE), Presenilin-1 (PSEN1) and Presenilin-2 (PSEN2), amyloid precursor protein (APP) and the linked mutations are some of the strongest risk factors that were observed to be associated with the brain disorder, Alzheimer’s." (PMID 27756223, 2016). "Involvement of APOE in multiple brain disorders such as TBI and AD indicates that APOE might play diverse roles in these processes." (PMID 26579811, 2015). "Several studies have confirmed that APOA-I and APOE function as immunosuppressants in various brain diseases, although the exact molecular mechanisms have not been elucidated." (PMID 36293147, 2022).
vasculopathy (26 papers, 2012 to 2026). "The biological mechanism of the island sign remains unclear, but its presence might be influenced by the underlying vasculopathy related to Apolipoprotein E (APOE) genotypes." (PMID 40051977, 2025). "Our findings indicate that the presence of the island sign may be influenced by the underlying vasculopathy related to APOE ε4, which increases amyloid deposition in the cerebral vasculature." (PMID 40051977, 2025). "Collectively, our study shows that the combined loss of Dscr-1 and ApoE causes metabolic dysfunction in the liver but reduces atherosclerotic plaques, thereby leading to a dramatic increase in serum cholesterol and the formation of sporadic vasculopathy." (PMID 33895138, 2021). "In this study, we aimed to explore this issue with a focus on vasculopathy in Seipin KO mice crossed into an atherosclerosis-prone apolipoprotein E (Apoe) KO background." (PMID 38525541, 2024). "Given the known effect of APOE ε4 on amyloid deposition in the cerebral vasculature, our findings indicate that APOE genotype-related vasculopathies may influence the presence of the island sign." (PMID 40051977, 2025). "Furthermore, LOX-1 transgenic/apoE−/− (LOXtg/apoE−/−) mice displayed augmented oxLDL uptake and accelerated inflammatory intramyocardial vasculopathy than control littermates." (PMID 23799016, 2013). "Plasma levels of APOE and other proteins may also provide insights into vasculopathy in particular individuals." (PMID 22485168, 2012).
infectious disease (24 papers, 2010 to 2025). A disorder directly resulting from the presence and activity of a microbial, viral, or parasitic agent in humans. "The APOE gene encodes 3 isoforms Ɛ4, Ɛ3 and Ɛ2 with APOE Ɛ4 associated with higher plasma cholesterol levels and increased pathogenesis in several infectious diseases (HIV, HSV)." (PMID 24116184, 2013). "In association with its immunomodulatory properties, apoE has an impact on the pathology of infectious diseases." (PMID 20109174, 2010). "As will be reviewed here, accumulating evidence indicates that apoE genotype could be an important host genetic factor affecting infectious disease risk." (PMID 20109174, 2010). "APOE ε4 is the ancestral APOE allele, as it is present in all great apes, while the shift to the APOE ε3 and APOE ε2 alleles may have reflected selective pressure from infectious diseases." (PMID 30412599, 2018). "The APOE Ɛ4 allele has been associated with an increased risk of Alzheimer’s disease, coronary heart disease and death after myocardial infarction as well as several infectious diseases including human immunodeficiency virus HIV, hepatitis C and herpes simplex virus (HSV)." (PMID 24116184, 2013). "While this immune response protects younger APOE ε4 carriers from infectious diseases, prolonged states of inflammation and cytokine release are likely deleterious with age34,35." (PMID 40665049, 2025). "The effect of the APOE genotype on survival and fertility was studied in a large population in rural Ghana in which mortality across the lifespan is dominated by infectious diseases." (PMID 28683096, 2017). "We examined survival and fertility, and their relationship with APOE ε4 in a large population in rural Ghana, which is characterized by high mortality from infectious diseases." (PMID 28683096, 2017). "Moreover, APOE ε4 appeared beneficial in certain infectious diseases evoked by both viruses (e.g., hepatitis C, HCV) and bacteria (e.g., malaria), though, on the contrary seemed rather detrimental in the case of human immunodeficiency virus (HIV) and herpes simplex virus (HSV) infections." (PMID 27457486, 2016). "Of the three common alleles of APOE, the so-called ‘thrifty’ ε4 allele is an ancestral allele that has been selected because it protects against some infectious diseases and increases cholesterol; thus, APOE ε4 may improve survival in populations experiencing food scarcity or poverty." (PMID 27168072, 2016). "We show novel findings that APOE ε4 did not negatively affect survival in a contemporary environment dominated by infectious diseases." (PMID 28683096, 2017).
bacterial infection (18 papers, 2014 to 2025). "Apolipoprotein E (APOE) was a novel diagnostic marker for invasive bacterial infections in pediatric patients." (PMID 34972134, 2021). "ApoC-I and ApoE are differentially expressed after bacterial infection in fish, and ApoA-IV is associated with food intake in zebrafish." (PMID 31722659, 2019). "APOE alleles, encoding a key lipid transport molecule, play a crucial determining role in the outcome of viral and bacterial infection." (PMID 24656052, 2014). "Systemic APOE ε4 pathways were broadly representative of conserved innate and adaptive immune responses to diverse viral and bacterial infections and pro-inflammatory stimuli, as well as generalized cytokine signaling and antigen presentation." (PMID 40709278, 2025). "Recent investigations have uncovered an additional facet of APOE's functionality, revealing its role in host defense against bacterial infections." (PMID 39880097, 2025). "Taken together, these results suggest that multifunctional APOE has an additional role in innate immunity during bacterial infection." (PMID 35740451, 2022). "Taken together, these results offer a new perspective on the role of intact apoE proteins in the immunological response to bacterial infections and the development of new alternatives to antibiotics." (PMID 34019903, 2021). "The goals of our study were to characterize the differential effects of two common bacterial infections and a Western diet on platelet inflammatory function and gene transcripts in ApoE-/- mice and in human samples." (PMID 26148065, 2015). "The goal of our study was to compare the differential effects of specific stimuli – two bacterial infections and a Western diet – on platelet responses in ApoE-/- mice, specifically examining inflammatory function and gene expression." (PMID 26148065, 2015). "Additionally, ApoE+CD11b+ AMs are glycolytic, highly phagocytic and modify the outcome of a secondary bacterial infection and of a chronic fibrotic response in vivo." (PMID 38671323, 2024). "APOE could be connected to the formation of aggregates, which is triggered by inflammatory activity, as a response to bacterial infection." (PMID 35740451, 2022). "Hypothetically, apoE could lead to the formation of aggregates as a neutralizing action against bacterial infection in an environment with high inflammatory activity." (PMID 34019903, 2021). "Indeed, apoE mimetic peptides have already been found to inhibit both viral and bacterial infections." (PMID 24751902, 2014). "Therefore, investigating these additional aspects, as well as how APOE isoforms compare to existing drugs, could drive the advancement of novel therapeutic approaches for combating bacterial infections." (PMID 39880097, 2025). "Furthermore, it has been reported that apoE is an isoform-dependent antioxidant, and neuroprotective effects and epidemiological study on patient cohorts showed that the apoE level in the blood can be used as a biomarker to diagnose bacterial infection." (PMID 34019903, 2021). "We also discuss other critical factors that may affect AD pathogenesis, including genetics, aging, variables related to environment, lifestyle habits, and describe the potential role of apolipoprotein E (APOE), viral and bacterial infection, sleep, and microbiota." (PMID 32677986, 2020).
inflammation (18 papers, 2008 to 2024). Aberrant reaction of the microcirculation characterized by movement of fluid and leukocytes from the blood into extravascular tissues. "This intensified inflammatory response served to neutralize the inhibitory effects of GSDME deficiency on vascular inflammation in ApoE−/− mice." (PMID 37761020, 2023). "Specifically, the apolipoprotein E‐deficient (ApoE−/−) mouse model can be used for modeling these CS‐induced diseases as it is susceptible to developing pronounced pulmonary inflammation and increased atherosclerotic plaque progression upon CS exposure." (PMID 33825214, 2021). "Our previous reports showed that IL-35 therapy inhibits EC activation, lung inflammation, inflammatory angiogenesis, and atherosclerotic lesions in ApoE–/– mice." (PMID 34622804, 2021). "In an ApoE(−/−) mouse model of vascular inflammation, it reduced leukocyte recruitment and systemic inflammation as measured by levels of pro-inflammatory mediators." (PMID 34073384, 2021). "Collectively, ApoE−/− mice that chronically consumed a Western-type diet for 20 weeks developed atherosclerotic plaques with vascular inflammation." (PMID 32967121, 2020). "Our results showed that iNOS is strongly expressed in liver of ApoE−/− mice and this increase plays, in turn, a critical role in the development of liver inflammation and OS." (PMID 29516009, 2018). "However, we have previously shown that ApoE-/- mice had more pulmonary inflammation than wild type mice after i.t. instillation of nanosized carbon black and there was vasomotor dysfunction in the exposed ApoE-/- mice as well." (PMID 22074227, 2011). "However, our objective was to determine whether the length of exposure to asbestos necessary to develop lung inflammation and early fibrosis was sufficient to elicit differences in aortic responses between ApoE−/− and DKO mice." (PMID 18795166, 2008).
psychiatric disorder (15 papers, 2016 to 2026). A disorder characterized by behavioral and/or psychological abnormalities, often accompanied by physical symptoms. "The lipoprotein E (ApoE) gene is a major genetic risk factor for late-onset psychiatric disorders." (PMID 39997742, 2025). "The following factors were found to be significantly different between the two groups of participants: gender, age, ApoE genotype, and comorbidity with psychiatric diseases." (PMID 39691160, 2024). "Notably, the strongest enrichment signal for AD and the three stress-related psychiatric disorders was for cholesterol metabolism, which included one enriched gene (APOE)." (PMID 39975850, 2025). "Twelve lead SNPs were located within 10 genes (BIN1, TMEM106B, AP001257.1, PICALM, SLC24A4, PVRL2, APOE, CLPTM1, CTB-179K24.3, and CASS4) for AD, and all three stress-related psychiatric disorders were identified using FUMA." (PMID 39975850, 2025). "Interactions, namely sex × PTSD, age × PTSD, APOE genotypes × PTSD, and psychiatric diseases × PTSD, were added to the multivariable logistic regression analysis to explore the effect of PTSD symptoms on the amyloid burden." (PMID 39691160, 2024). "The findings imply a close relationship between PTSD and brain Aβ levels, irrespective of sex, age, ApoE genotype, or psychiatric diseases." (PMID 39691160, 2024). "The association between PTSD symptoms and Aβ levels was not affected by sex, age, ApoE genotype, or psychiatric diseases." (PMID 39691160, 2024). "The current findings imply that PTSD symptoms are associated with a higher global brain Aβ burden, irrespective of sex, age, ApoE genotype, or comorbid psychiatric diseases." (PMID 39691160, 2024).
genetic disorder (14 papers, 2011 to 2025). "Apolipoprotein E (APOE 19q32.13) ε4 allele has been considered the main genetic disorder responsible for the sporadic form." (PMID 36819480, 2022). "The administration of APOE genetic test should be performed in a dedicated genetic counselling process, as appropriate for neurological late-onset genetic disorders." (PMID 40761402, 2025). "Previous studies from our group and others have shown that healthy carriers of apoE variants are very common, implicating that LPG is a dominant genetic disease with incomplete penetrance." (PMID 31092271, 2019). "Although AD is not a conventional genetic disease, numerous studies have shown that apolipoprotein E (APOE) is a major risk gene for the progression of AD, with APOE4 increasing the risk of AD and APOE2 preventing AD." (PMID 40076831, 2025). "Whether different isoforms of ApoE can modulate ADan aggregation in FDD, a genetic disorder comparable to familial AD, remains to be determined." (PMID 36436561, 2022).